ZNF625-ZNF20 (ZNF625-ZNF20 readthrough (NMD candidate))
Gene: Protein-coding gene on chromosome 19 (12,132,117 to 12,156,731, reverse strand). Ensembl gene ENSG00000213297.
Genetic constraint (gnomAD): Missense variants: 56 observed, 84.68 expected, observed/expected ratio (o/e) 0.66, 90% interval 0.53 to 0.83. Synonymous variants: 24 observed, 29.6 expected, observed/expected ratio (o/e) 0.81, 90% interval 0.59 to 1.14.